RUFY2 (RUN and FYVE domain containing 2)
Synonyms: KIAA1537; RABIP4R; FLJ10063; ZFYVE13
Tractability: PROTAC: ubiquitination databases record sites on it; its protein half-life has been measured.
Safety:
Unwanted effects reported when the protein is acted on. In parentheses: how it was acted on, where the effect was seen, and who reports it.
creatinine clearance (source: ClinPGx)
Gene: Protein-coding gene on chromosome 10 (68,341,107 to 68,407,313, reverse strand). Ensembl gene ENSG00000204130.
Subcellular location: Nucleus
Subcellular location (Human Protein Atlas): Nucleoplasm
Gene Ontology:
Molecular function: SH3 domain binding; metal ion binding
Biological process: regulation of endocytosis
Cellular component: cytoplasm; endosome; nucleus
Genetic constraint (gnomAD): Loss-of-function variants: 28 observed, 49.43 expected, observed/expected ratio (o/e) 0.57, 90% interval 0.42 to 0.78. The upper end of that interval is the gene's LOEUF score, 0.78, which puts it in group 3 of 6, group 1 being the genes least tolerant of losing a copy. Missense variants: 326 observed, 463.16 expected, observed/expected ratio (o/e) 0.7, 90% interval 0.64 to 0.77. Synonymous variants: 171 observed, 157.17 expected, observed/expected ratio (o/e) 1.09, 90% interval 0.96 to 1.24.
Homologues: Orthologues: chimpanzee RUFY2 (100% identical), macaque RUFY2 (100% identical), dog RUFY2 (99% identical), rabbit RUFY2 (98% identical), pig RUFY2 (96% identical), mouse Rufy2 (95% identical), guinea pig RUFY2 (91% identical), rat Rufy2 (90% identical), zebrafish rufy2 (78% identical), tropical clawed frog rufy2 (50% identical), Drosophila melanogaster CG31064 (44% identical), Drosophila melanogaster CG6051 (14% identical), and 1 more. Paralogues in human: RUFY1 (62% identical), RUFY3 (52% identical), ZFYVE26 (21% identical), SNX29 (19% identical), PLEKHM2 (18% identical), ZFYVE28 (17% identical), RUNDC3B (17% identical), RUNDC3A (17% identical), ZFYVE1 (15% identical), ZFYVE19 (11% identical), ZFYVE16 (10% identical), PLEKHF1 (8% identical), and 1 more.
Diseases named in the same sentence as RUFY2 in open-access papers:
RUFY2 is named in the same sentence as 7 diseases in open-access papers, as found by Europe PMC text mining. Sharing a sentence is not in itself a finding about the gene and the disease. The quoted sentences say what the papers report.
glioblastoma (2 papers, 2020 to 2023). The most malignant astrocytic tumor (WHO grade IV). "RUFY2 expression correlates negatively with risk of glioblastoma." (PMID 37347215, 2023).
late-onset Alzheimers disease (1 paper, 2014). This is the most common form of the disease, which happens to people age 65 and older. "Other genes mapping in the deleted region, including DNAJC12 (MIM 606060), HERC4 (MIM 609248), PBLD (MIM 612189), HNRNPH3 (MIM 602324), RUFY2 (MIM 610328), STOX1 (MIM 609397), and CTNNA3 (MIM 607667), have been linked to late-onset Alzheimer’s disease (AD6; MIM 605526)." (PMID 24297458, 2014).
neuroblastoma (1 paper, 2023). Neuroblastoma (NB) is the most common solid, extracranial childhood tumor. "There are almost no relevant studies on the RUFY2 gene in neuroblastoma, and the relationship between the RUFY2 gene and neuroblastoma remains to be elucidated." (PMID 37347215, 2023).
cancer (2 papers, 2020 to 2023). A tumor composed of atypical neoplastic, often pleomorphic cells that invade other tissues. "The RUN and FYVE domain containing 2 (RUFY2) gene has been found to frequently be mutated in high‐microsatellite instability cancers." (PMID 37347215, 2023). "Like RUFY1, a role for RUFY2 in various cancer has been reported." (PMID 32850870, 2020).
tumor (2 papers, 2020). "Predictions based on the ENSG00000203739/ENSG00000271646-miR-637-CYBRD1 and TPTEP1-miR-196a-5p-RUFY2 regulation axes indicated that the two proteins may act as an oncogene and tumor suppressor, respectively, in the development of GBM." (PMID 32211330, 2020). "When overexpressed, miR-196a-5p impedes translation of RUFY2, a putative tumor suppressor protein." (PMID 32211330, 2020). "Based on the theory of ceRNA, we found potential ncRNA regulatory pathways involving an oncogene and a tumor suppressor, ENSG00000203739/ENSG00000271646-miR-637-CYBRD1 and TPTEP1-miR-196a-5p-RUFY2, and constructed a local PPI network which might contribute to proliferation and invasion of GBM." (PMID 32211330, 2020).
RUFY2 also shares sentences with these, for which no sentence is quoted: non-small cell lung carcinoma (1 paper); ovarian carcinoma (1).